PRSS21 (serine protease 21)
Description:
Could regulate proteolytic events associated with testicular germ cell maturation.
Synonyms: ESP-1; ESP1; TEST1; TESTISIN
Tractability: Antibody: UniProt places it where antibodies can reach, with high confidence; its Gene Ontology location is reachable by antibodies, with high confidence; UniProt predicts a signal peptide or a membrane-spanning region. PROTAC: ubiquitination databases record sites on it.
Gene: Protein-coding gene on chromosome 16 (2,817,180 to 2,826,304, forward strand). Ensembl gene ENSG00000007038.
Subcellular location: Cell membrane
Subcellular location (Human Protein Atlas): Cytosol; Mid piece; Principal piece
Pathways (Reactome):
Metabolism of proteins: Post-translational modification: synthesis of GPI-anchored proteins
Gene Ontology:
Molecular function: protein binding; serine-type endopeptidase activity; serine-type peptidase activity
Biological process: proteolysis; spermatogenesis
Cellular component: cytoplasm; extracellular region; membrane; plasma membrane
Genetic constraint (gnomAD): Loss-of-function variants: 40 observed, 27.17 expected, observed/expected ratio (o/e) 1.47, 90% interval 1.14 to 1.86. The upper end of that interval is the gene's LOEUF score, 1.86, which puts it in group 6 of 6, group 1 being the genes least tolerant of losing a copy. Missense variants: 467 observed, 399.02 expected, observed/expected ratio (o/e) 1.17, 90% interval 1.08 to 1.26. Synonymous variants: 186 observed, 158.58 expected, observed/expected ratio (o/e) 1.17, 90% interval 1.04 to 1.33.
Homologues: Orthologues: chimpanzee PRSS21 (99% identical), mouse Prss21 (65% identical), rat Prss21 (65% identical), pig PRSS21 (61% identical), tropical clawed frog prss29 (37% identical), Drosophila melanogaster Sb (31% identical), Drosophila melanogaster CG17242 (17% identical). Paralogues in human: PRSS41 (51% identical), HPN (35% identical), TMPRSS13 (35% identical), TMPRSS6 (34% identical), PRSS22 (33% identical), TMPRSS11F (33% identical), TMPRSS7 (33% identical), TMPRSS9 (33% identical), TMPRSS11D (32% identical), ST14 (32% identical), TMPRSS3 (32% identical), TMPRSS11B (31% identical), and 5 more.
Diseases named in the same sentence as PRSS21 in open-access papers:
PRSS21 is named in the same sentence as 19 diseases in open-access papers, as found by Europe PMC text mining. Sharing a sentence is not in itself a finding about the gene and the disease. The quoted sentences say what the papers report.
gastric cancer (2 papers, 2021 to 2022). A primary or metastatic malignant neoplasm involving the stomach. "High expression of ONECUT2 and PRSS21 have been reported to be associated with poorer prognosis in various cancers including prostate cancer, hepatocellular carcinoma, and gastric cancer." (PMID 35754804, 2022). "We found that high expression of CPVL, ONECUT2, DDC, PRSS21, and GRTP1 increase the risk of gastric cancer." (PMID 35754804, 2022). "The high risk-scores of CPVL, ONECUT2, DDC, PRSS21, and GRTP1 could be used to determine the degree of malignancy and prognosis in gastric cancer patients." (PMID 35754804, 2022). "To find out the role of hub genes in the overall survival of gastric cancer we performed a multivariate Cox regression analysis, among 21 hub genes, the eight genes (KCNJ3, CPVL, ONECUT2, SLC19A3, DDC, PRSS21, F12, and GRTP1) were designated as independent indicators of poor prognosis." (PMID 35754804, 2022).
Infertility (2 papers, 2014 to 2022). "Investigations in male mice have found that loss-of-function mutations in genes involved in the production of headless spermatozoa, such as Spata6, Hook1, Prss21, Oaz3, and Odf1, can cause fertility reduction or infertility." (PMID 36028792, 2022). "Uterine fluids seem to partially rescue the infertility status of acrosine and PRSS21 knockout spermatozoa, implying that a compensatory mechanism for the loss of both ACR and PRSS21 exists." (PMID 25054321, 2014).
prostate carcinoma (2 papers, 2021 to 2022). A carcinoma that arises from epithelial cells of the prostate gland. "However, the role of PRSS21 in prostate cancer needs further exploration." (PMID 34540835, 2021).
seminoma (2 papers, 2020 to 2022). A radiosensitive malignant germ cell tumor found in the testis (especially undescended), and extragonadal sites (anterior mediastinum and pineal gland). "Seminomas are known to show selective hypermethylation at several tumor suppressors, such as MGMT, SCGB3A1, RASSF1A, HIC1, and PRSS21." (PMID 32176716, 2020). "It has also been shown that gain in PRSS21 DNA methylation may be used to diagnostic indicator of the presence of TGCT subtype non-seminoma, where the subtype seminoma would show loss of DNA methylation." (PMID 35774118, 2022).
cervical cancer (1 paper, 2022). A primary or metastatic malignant neoplasm involving the cervix. "However, despite the involvement of PRSS21 in TGCT development, it was found not to be expressed in embryonal carcinoma cell lines derived from testicular tumours but was found to be expressed in the cervical cancer cell line HeLa and melanoma cell lines." (PMID 35774118, 2022).
metastatic disease (1 paper, 2024). "Notably, PRSS21, which was under-expressed in Black patients with localized or regional disease, was overexpressed in Black patients with metastatic disease." (PMID 39580376, 2024). "However, the expression of PRSS21 shifted from being highly under-expressed in localized and regional disease to overexpressed in metastatic disease." (PMID 39580376, 2024).
ovarian carcinoma (1 paper, 2025). A malignant neoplasm originating from the surface ovarian epithelium. "The PRSS21 gene, which encodes protein testisin, is associated with ovarian cancer prognosis." (PMID 41465326, 2025).
prostate tumors (1 paper, 2021). "Compared to normal tissues, ARHGEF38, NETO2, GOLM1, and SAPCD2 were hypomethylated in prostate tumors, while PRSS21 was hypermethylated in prostate tumors compared, which may be the underlying mechanism for the abnormal expression of the five genes in PCa." (PMID 34540835, 2021).
tumor (10 papers, 2012 to 2025). "PRSS21 is a tumour suppressor gene silenced by aberrant methylation in testicular germ cell tumours." (PMID 26861414, 2016). "For example, the serine proteases PRSS3 (also known as trypsinogen IV), PRSS8 (prostasin), and PRSS21 (testisin) were categorized as tumor-protective proteases in the human degradome." (PMID 22761798, 2012). "In particular PRSS21, which is associated with TEX101 in curated databases, has been shown to be involved in initiation and progression of TGCT and is thought to act as a tumour suppressor." (PMID 35774118, 2022). "Finally, we observed that these genes, except PRSS21, were highly expressed in tumor samples and PCa cells." (PMID 34540835, 2021). "Three genes: PRSS21, FOXQ1, and MMP7, formed a highly upregulated cluster exhibiting a fold increase greater than 220-fold in tumor tissues (Median (Range) = 1273 (228–1598) fold increase)." (PMID 41465326, 2025). "Three genes (PRSS21, FOXQ1, and MMP7) formed a highly upregulated cluster, with a fold increase greater than 220 in tumor tissues." (PMID 41465326, 2025). "This difference in expression both between normal testis and TGCT tissue as well as TGCT tissue and non-testis cell lines led to the belief that PRSS21 acts as a tumour suppressor in TGCT." (PMID 35774118, 2022).
PRSS21 also shares sentences with these, for which no sentence is quoted: cancer (4 papers); ovarian tumor (2); colon cancer (1); colorectal cancer (1); embryonal carcinoma (1); hepatocellular carcinoma (1); infection (1); melanoma (1); testicular dysgenesis syndrome (1); testicular tumours (1).